TGFA (transforming growth factor alpha)
Diseases named in the same sentence as TGFA in open-access papers (continued):
Sharing a sentence is not in itself a finding about the gene and the disease.
lung disease (7 papers, 2012 to 2025). "TGFα mice on Dox for 6 weeks develop severe fibrotic lung disease including subpleural and adventitial thickening and the loss of lung function." (PMID 32761869, 2020). "We used OCT-based indentation to characterise diaphragm dysfunction in a transgenic mouse model of transforming growth factor-alpha (TGF-α)-induced lung disease." (PMID 28473708, 2017). "TGFα was found upregulated in multiple fibrotic lung diseases including IPF and cystic fibrosis." (PMID 31156440, 2019). "Body weight was found to decline in the CCSP/TGFα cohort as compared with the CCSP/- (control) cohort, which is typical for this lung disease model." (PMID 41150169, 2025).
meningioma (7 papers, 2010 to 2024). A generally slow growing tumor attached to the dura mater. "Epidermal growth factor receptor (EGFR) can be activated through an autocrine loop by expression of EGFR ligands, EGF, and TGF-alpha (transforming growth factor alpha; increased expression linked to aggressive meningioma proliferation)." (PMID 25485306, 2014). "In the present study we have demonstrated that EGFR and its ligands EGF and TGFα are widely expressed in human meningiomas and that the receptor appears to be in an activated state." (PMID 28367377, 2017). "Similarly, the epidermal growth factor receptor (EGFR), and both their EGF and transforming growth factor-alpha (TGFα) ligands, as well as some members of the insulin-like growth factor (IGF) system (e.g. IGF2), have all been associated with meningioma cell proliferation and tumor progression." (PMID 25965831, 2015).
thyroid cancer (7 papers, 2010 to 2025). "Meta-review of thyroid cancer gene expression profiling studies identifies important diagnostic biomarkers, including relatively novel or uncharacterized genes such as TGFA." (PMID 25015300, 2014). "TGFA and EGFR have been previously found to be co-expressed in thyroid cancer and have been associated with a more aggressive disease." (PMID 20877637, 2010). "Recently, gene expression analyses have identified TGFA upregulation in thyroid carcinomas, especially in PTCs." (PMID 20877637, 2010). "Furthermore, PTC clinical samples analyzed by real-time RT-PCR expressed EGFR transcript levels similar to those of 5 normal thyroid tissues from patients with pathologies other than thyroid cancer, whereas significantly elevated levels of TGFA transcripts were only present in PTCs." (PMID 20877637, 2010). "Subsequently, real-time RT-PCR analysis of TGFA and EGFR transcripts was performed on total RNA from 5 normal thyroid tissue samples from pathologies other than thyroid cancer and 23 PTC biopsies." (PMID 20877637, 2010). "Transforming growth factor-alpha (TGF-α), a key ligand of the epidermal growth factor receptor (EGFR), plays a pivotal role in promoting drug resistance across multiple cancer types, including thyroid cancer." (PMID 40843353, 2025). "However, prior to the current study, a functional TGFA/EGFR signaling loop has not been experimentally demonstrated in thyroid cancer." (PMID 20877637, 2010).
cholesteatoma (6 papers, 2005 to 2023). A pathologic process characterized by the proliferation of keratinizing squamous epithelium resulting in the accumulation of keratin and cells in the middle ear and/or mastoid. "Cholesteatoma tissue is also the source of pro-inflammatory cytokines such as IL-1, transforming growth factor alpha (TGF-α), pro-angiogenic factors, and various enzymes." (PMID 25385222, 2015). "A study covering expression and distribution of transforming growth factor alpha (TGF) in the middle ear suggests that autocrine and paracrine stimulation of TGF in the cholesteatoma squamous epithelium may contribute for its proliferation." (PMID 16446916, 2005). "Moreover, many of these cytokines promote peri-matrix angiogenesis (EGF, PDGF, IL-8, TGFα) and osteoclastogenesis/bone resorption (IL-1, IL-6, PTHrP, receptor activator of nuclear factor kappa-B ligand (RANKL), which are both responsible for cholesteatoma proliferation and local aggressiveness." (PMID 37623440, 2023).
depression (6 papers, 2020 to 2023). "The AG genotype of the rs2166975 TGFA was associated with an increased risk of depression development, while the GG genotype of the rs2166975 TGFA reduced the risk." (PMID 37510364, 2023). "In our study, we were the first to show a link between rs2166975 polymorphism of TGFA and depression." (PMID 32140313, 2020). "The results demonstrated that the A/G genotype of the g.70677994G>A (rs2166975) polymorphism of the TGFA gene is associated with an increased risk of depression development, while G/G genotype decreased this risk." (PMID 32140313, 2020). "Moreover A/G-G/T genotype of rs5029748 IKBKB and rs2166975—TGFA, increased risk of depression but G/T-T/T are associated with lower risk of disease." (PMID 32140313, 2020). "Nevertheless, our findings confirm at least a partial association between TGFA, TGFB, PTGS2, IRF1 and IKBKB genes and depression, and hence it is highly likely that inflammation plays a role in psychiatric disorders." (PMID 33946816, 2021). "This is the first set of such results concerning the role of TGFA in depression or other psychiatric disorders." (PMID 33946816, 2021). "Summarizing, our results confirm at least a partial association between TGFA, TGFB, IRF1, PTGS2 and IKBKB and depressive disorders." (PMID 33946816, 2021). "In reference to effect of combined genotypes, it was found that G/G-T/T genotypes of g.70677994G>A (rs2166975)—TGFA and g.186640617C>T (rs4648308)—PTGS2 was associated with decreased risk of depression occurrence, while A/G-C/T genotypes increased this risk." (PMID 32140313, 2020). "We observed that A/G of the rs2166975 TGFA, A/C of rs2070729 IRF1 and G/T of rs5029748 IKBKB were associated with an increased risk of depression development while the T/T of rs5029748 IKBKB, T/T of rs4648308 PTGS2 and G/G of rs2166975 TGFA reduced this risk." (PMID 32140313, 2020). "Gene-gene interactions of rs1800469 (TGFB1), rs2070729 (IRF1), rs5275 (PTGS2), rs4648308 (PTGS2), rs2166975 (TGFA), rs5029748 (IKBKB) and the risk of depression occurrence." (PMID 32140313, 2020). "Distribution of genotypes and alleles of rs1800469 (TGFB1), rs2070729 (IRF1), rs5275 (PTGS2), rs4648308 (PTGS2), rs2166975 (TGFA), rs5029748 (IKBKB) and the risk of depression occurrence." (PMID 32140313, 2020). "Distribution of genotypes and alleles of rs2070729 (IRF1), rs5275 (PTGS2), rs4648308 (PTGS2), rs2166975 (TGFA), rs5029748 (IKBKB) and the risk of depression occurrence in male and female population." (PMID 32140313, 2020). "Concluding, our results indicate that TGFA, TGFB, PTGS2, IRF1 and IKBKB could be associated with depression and its treatment." (PMID 36012250, 2022). "This study focuses on the contribution of genes such as IRF1, PTGS2, IKBKB, TGFA and TGFB in the molecular basis of depression as well as the impact of chronic agomelatine administration." (PMID 36012250, 2022). "The present study is the first to investigate the levels of TGFA, IRF1 and IKBKB mRNAs in an animal model of depression." (PMID 33946816, 2021). "The reduced models showed that transforming growth factor-alpha (TGF-α) and female sex predicted higher levels of depression, while growth-regulated oncogenes predicted lower levels of depression." (PMID 33578686, 2021). "Our key findings reveal that TGFA, TGFB, PTGS2, IRF1 and IKBKB could be responsible for immune system activation in depression." (PMID 36012250, 2022). "In this research, we genotyped six polymorphic variants of TGFA, TGFB1, IRF1 and PTGS2 genes; and to our knowledge, none of this SNPs have been studied in the context of severity and treatment response in depression before." (PMID 32140313, 2020).
Hyperglycemia (6 papers, 2013 to 2023). An increased concentration of glucose in the blood. "According to our data, hyperglycemia alone caused upregulation of a number of genes such as TGFA, CDCA5, MUC3A and C3AR1." (PMID 37511575, 2023).
renal carcinoma (6 papers, 2004 to 2021). A carcinoma arising from the epithelium of the renal parenchyma or the renal pelvis. "Down-regulation of EGFR or TGFα using RNAi or their pharmacological targeting with blocking antibodies resulted in inhibition of the proliferation of in vitro cellular models of renal cancer." (PMID 34399807, 2021). "For example, HIF-2α is necessary to maintain tumour growth in RCC4 renal carcinoma cells, potentially via regulation of the cell cycle regulatory proteins TGFα and cyclin D1." (PMID 20637078, 2010). "Unlike, some other genes involved in renal cancer proliferation, such as cyclin D1 (CCND1), transforming growth factor alpha (TGFA) and the amino acid carrier SLC7A5 are preferentially induced by HIF2α." (PMID 33321829, 2020).
squamous cell carcinoma (6 papers, 1989 to 2024). A carcinoma arising from squamous epithelial cells. "The expression of TGFA protein is low in normal cervical tissues and upregulated in squamous cell carcinoma tissues, and the expression of TGFA protein increases gradually with the decrease of tumour differentiation." (PMID 38152044, 2024). "TGFA expression is elevated in the hypopharyngeal squamous cell carcinoma cell line BICR6 that harbors a focal CN gain involving the TFGA locus, similar to that of TNBC tumor samples (TN-M4 in the present study and TCGA-AR-A256 in TCGA), according to Cancer Cell Line Encyclopedia (CCLE) data." (PMID 28636652, 2017). "Autoregulation of the synthesis of transforming growth factor-alpha (TGF-alpha) was investigated at the message and protein levels in spheroid and monolayer cultures prepared from the A431 human squamous carcinoma cell line." (PMID 1739610, 1992).
ulcer (6 papers, 2010 to 2025). "It was, therefore, proposed that H. pylori may in fact, antagonize, aspirin-induced delay of ulcer healing due to suppression of acid secretion by the enhancement in PGE2 possibly derived from COX-2 expression and activity and to the overexpression of growth factors such as TGFα and VEGF." (PMID 27275302, 2015).
chordoma (5 papers, 2011 to 2022). Chordomas are rare malignant tumors arising from embryonic remnants of the notochord in axial skeleton. "Expression of basic fibroblast growth factor (bFGF), transforming growth factor alpha (TGF alpha) and fibronectin was reported to correlate with an increased incidence of disease recurrence in chordoma." (PMID 22613809, 2011). "Although not explored in our xenograft, EGF and TGFα were reported to be highly expressed in 22 chordoma samples (100%) in a previous study." (PMID 24260133, 2013). "Specific to the CF466 sacral chordoma model, TGFA was among the most significantly reduced genes, which is notable because it encodes an EGFR ligand, and SINE compounds are effective against cancer cells with engineered resistance to EGFR-tyrosine kinase inhibitors." (PMID 36059685, 2022).
cleft lip (5 papers, 2012 to 2022). Congenital defect in the upper lip where the maxillary prominence fails to merge with the merged medial nasal prominences. "We found an association between a single nucleotide polymorphism in the intron of the TGFA gene with cleft lip/palate." (PMID 23029012, 2012). "Markers located within and flanking the IRF6 and TGFA genes were tested for association with cleft of the lip or palate under a case-control design." (PMID 23029012, 2012). "The association of the transforming growth factor alpha (TGFA) gene at 2p13 with cleft lip/palate has also rendered intriguing results." (PMID 23029012, 2012). "We speculated on the attributable fraction for the interaction of IRF6 and TGFA genes to the risk of cleft lip/palate using the Brazilian case-control sample and three additional family or case series data sets comprising a total of 8,717 individuals." (PMID 23029012, 2012). "TGFA was the first gene associated to isolated cleft lip/palate in a case-control study and was selected as a candidate gene because of its expression on palatal tissue in culture and its presence at high levels in the medial epithelial edge of the palatal shelves at the time of palatal fusion." (PMID 23029012, 2012). "TGFA encodes a growth factor that activates a signaling pathway for cell proliferation, differentiation and development, and OMIM links include cancers, cleft lip and Alstrom syndrome." (PMID 29691431, 2018). "Meta-analytic approaches concluded that TGFA plays a small but significant role in cleft lip/palate with odds ratios indicating a modest effect size." (PMID 23029012, 2012). "For many of the other genes previously associated with cleft lip/palate, including TGFA, a variety of positive and negative results have been reported, and TGFA has been largely ignored in the recent years." (PMID 23029012, 2012). "Therefore interaction between IRF6 and TGFA in tooth agenesis may also be relevant to cleft lip/palate." (PMID 23029012, 2012). "Therefore, we hypothesized interaction between IRF6 and TGFA may also be relevant to cleft lip/palate." (PMID 23029012, 2012). "Analysis of the pooled samples indicates statistical interaction between a marker at TGFA (rs1807968) and another marker at IRF6 (rs2013162) in the cleft lip only group (P = 0.003)." (PMID 23029012, 2012). "Since tooth agenesis is commonly found in individuals with cleft lip/palate, we used three large samples of cleft cases to test for interaction between IRF6 and TGFA in the etiology of the cleft phenotype." (PMID 23029012, 2012). "Since tooth agenesis is commonly found in individuals with cleft lip/palate (CL/P), we used four large cohorts to evaluate if IRF6 and TGFA interaction contributes to CL/P." (PMID 23029012, 2012).
ischemia (5 papers, 2014 to 2023). A hypoperfusion of the BLOOD through an organ or tissue caused by a PATHOLOGIC CONSTRICTION or obstruction of its BLOOD VESSELS, or an absence of BLOOD CIRCULATION. "An effect of TGFα on hippocampal neurogenesis and memory performance has also been described in the hippocampus in models of ischemia." (PMID 33335309, 2021). "Interestingly, behavioral alterations have been found in individuals with disrupted neuregulin signaling and cognitive improvement has been observed in mouse models of ischemia upon treatment with TGFα." (PMID 33335309, 2021).
orofacial cleft (5 papers, 2012 to 2025). A disorder of facial skeleton that is characterized by cleft lip and/or cleft palate that result in feeding, speech and hearing problems caused by failures during development. "TGFA has also been associated with orofacial clefts, and a previous study using the case-parent trio design raised the possibility that IRF6 and TGFA interact and lead to orofacial clefts, supporting the finding from our group." (PMID 33406080, 2021). "Interestingly, genetic interactions between TGFA and IRF6 (i.e. co-transmission of risk alleles with higher than expected frequency) were reported to contribute to the risk for tooth agenesis as well as orofacial clefts." (PMID 25360592, 2014).
pancreatic adenocarcinoma (5 papers, 2006 to 2025). "Using in silico platforms, it was confirmed that TGFA, the gene encoding TGFα, is significantly overexpressed in pancreatic adenocarcinomas relative to normal pancreatic tissues." (PMID 40410803, 2025). "Using multiple in silico tools, it was confirmed that TGFA is significantly overexpressed in pancreatic adenocarcinomas compared to normal pancreatic tissues." (PMID 40410803, 2025). "Expression of TGFα forms was also analyzed in patient-derived xenografts (PDXs) obtained from twelve different pancreatic adenocarcinomas." (PMID 40410803, 2025). "Moreover, pancreatic adenocarcinomas were among the tumoral tissues in which expression of TGFA was higher when compared to other neoplasias." (PMID 40410803, 2025). "Moreover, the transforming growth factor alpha (TGF-alpha) is abundant in pancreatic nerves, and the epidermal growth factor receptor (EGFR) is prominent in adenocarcinoma cells, constituting a growth advantage of pancreatic adenocarcinoma." (PMID 37297000, 2023).
schizophrenia (5 papers, 2021 to 2025). A major psychotic disorder characterized by abnormalities in the perception or expression of reality. "In the current study, we found significantly higher levels of transforming growth factor alpha and platelet-derived growth factor (subunit AA) in patients with schizophrenia compared with healthy individuals." (PMID 37185739, 2023).
triple-negative breast carcinoma (5 papers, 2016 to 2026). An invasive breast carcinoma which is negative for expression of estrogen receptor (ER), progesterone receptor (PR), and human epidermal growth factor receptor 2 (HER2). "It was shown that incubation of BT-20 cells (triple-negative breast cancer cells) with Transforming growth factor-alpha (TGF-α) and A23187, a mobile ion-carrier, caused 13-HODE formation which was dependent on the Epidermal growth factor (EGF) / TGF-α." (PMID 34838055, 2021).
adenoma (4 papers, 2001 to 2023). A neoplasm arising from the epithelium. "However, TGFα encoding mice fed recommended levels of selenium (0.1 ppm) had larger adenomas and carcinomas than mice fed supranutritional levels of selenium (0.4 or 2.25 ppm) and these TGFα mice had larger carcinomas than selenium-deficient mice." (PMID 23460847, 2013). "Both the control and TrsptG37/+ mice appeared to develop more adenomas than TGFα/+ or bi-transgenic mice." (PMID 23460847, 2013). "However, adenoma and carcinoma size and area were smaller in TGFα transgenic mice that were fed 0.4 and 2.25 versus 0.1 ppm of selenium." (PMID 23460847, 2013). "Mice harboring the TGFα transgene (Groups 1 and 3) had a significantly greater formation of adenomas, carcinomas, and both adenomas and carcinomas than mice lacking the TGFα transgene (Groups 2 and 4; all p<0.01)." (PMID 23460847, 2013).
chronic kidney disease (4 papers, 2013 to 2025). Impairment of the renal function secondary to chronic kidney damage persisting for three or more months. "Moreover, TIMP3 is the only known physiological inhibitor of ADAM17, a metalloprotease responsible for shedding of several ligands, in particular HB-EGF and TGFα, which are involved in the pathogenesis of chronic kidney disease and glomerulonephritis." (PMID 23401241, 2013).
chronic pancreatitis (4 papers, 2015 to 2023). A chronic inflammatory process causing damage and fibrosis of the pancreatic parenchyma. "Metaplastic lesions of chronic pancreatitis patients regularly express high levels of the epidermal growth factor receptor (EGFR) family and their natural ligands EGF and TGFα." (PMID 26697077, 2016). "The combination of TGFα overexpression and Smad4 deletion in the pancreas of the STP mice presented a number of histologic similarities to human chronic pancreatitis, including increased fibrosis and development of PanIN-1& -2 lesions." (PMID 25803032, 2015).
pancreatitis (4 papers, 2006 to 2017). Inflammation of the pancreas. "(B) qRT-PCR for Egfr, Egf, Tgfα, Mmp2 and Mmp9 expression in fibroblasts freshly sorted from control normal pancreata, iKras* pancreata 3 weeks post pancreatitis, iKras* and iKras*;CD11b-DTR pancreata 3 days post Kras* inactivation and DT treatment." (PMID 28980940, 2017). "(A) qRT-PCR for Egf, Tgfα, Hbegf, Areg, Ereg, Mmp1, Mmp2, Mmp9, Mmp12 and Mmp14 expression in littermate control, iKras* pancreata 3 weeks post pancreatitis, iKras* and iKras*;CD11b-DTR pancreata 3 days post Kras* inactivation and DT treatment." (PMID 28980940, 2017). "(G) qRT-PCR for Egf, Tgfα, Hbegf, Tgfβ1 and Tnfα expression in myeloid cells sorted from control spleen, iKras* pancreata 3 weeks post pancreatitis and 3 days post Kras* inactivation." (PMID 28980940, 2017). "(D) qRT-PCR for transgenic Kras*, Fn1, Col1a1, Col3a1, Shh, Hbegf, Ereg, Areg, Tgfα and Egf in littermate control and iKras*;CD11b-DTR pancreata 3 weeks post pancreatitis and in iKras*;CD11b-DTR pancreata following DT treatment for 3 days and 1 week." (PMID 28980940, 2017).